NPY (neuropeptide Y)
Diseases named in the same sentence as NPY in open-access papers (continued):
Sharing a sentence is not in itself a finding about the gene and the disease.
migraine (continued). "NPY may be involved in pathogenesis of weight gain seen in patients with migraine under preventive medication." (PMID 29442286, 2018). "We have tried to rationalize these potential sites of action with what we know of NPY and how it might fit into a role in migraine pathophysiology." (PMID 27023421, 2016). "Reported migraine triggers (skipping meals) or symptoms (appetite changes) might act through NPY because altered feeding behavior is able to interfere with NPY pathways." (PMID 27023421, 2016). "NPY targeting within the MHb might emerge as a new and effective migraine treatment." (PMID 37231359, 2023). "A study found that insulin resistance amongst non-obese premenopausal women with chronic migraine could be mediated by NPY, as fasting levels were found to be elevated, demonstrating a possible link between migraine and these other disorders via feeding pathways." (PMID 37569369, 2023). "In addition, prospective sampling of blood and cerebrospinal fluid can be used to examine whether concentrations of orexins, NPY, and dopamine differ between the premonitory, ictal, postdromal, and interictal phase of migraine." (PMID 36514014, 2022). "The microinjection of NPY into the medial habenula (MHb) exhibited analgesic and anxiolytic-like effects in the mouse model of glyceryl trinitrate (GTN)-induced migraine." (PMID 38397400, 2024). "Here, our findings uncover that the MHb acts as an additional action site for NPY’s analgesic effects and uniquely inhibits GTN-induced migraine-like pain." (PMID 37231359, 2023). "Other receptors with possible indirect effects on migraine are parathyroid hormone 1 receptor (PTH1R) and PTH2R, which mediates calcium and phosphate homeostasis, and NPY5R that acts as receptor for neuropeptide Y (NPY), PYY, and PYY, and influences eating." (PMID 35453627, 2022). "In this study, CGRP, PACAP, NPY, VIP, and nociceptin were recorded at different times after stimulation to explore the dynamic changes in the neuropeptides during migraine attacks." (PMID 34963819, 2021). "The improved rat model of migraine with repeated stimulation of TG resulted in a more pronounced elevation of CGRP, PACAP, and NPY." (PMID 34963819, 2021). "Several other neuropeptides involved in migraine, such as pituitary adenylate cyclase activating polypeptide (PACAP), vasoactive intestinal peptide (VIP), neuropeptide Y (NYP), and nociception, have also been studied." (PMID 34963819, 2021). "The HTH hosts many key neuropeptide systems, such as orexins, oxytocin, neuropeptide Y, and pituitary adenylate cyclase activating protein(PACAP), etc., which have been postulated to play a role in migraine pathophysiology." (PMID 31244765, 2019). "Neuropeptide Y (NPY) has been demonstrated to be involved in the modulation of pain and emotion, and may play a role in migraine pathophysiology." (PMID 37231359, 2023). "Next, we microinjected NPY into the medial habenula (MHb), and further infused Y1 or Y2 receptor agonists into the MHb, respectively, to detect the effects of NPY in GTN-induced migraine-like behaviors." (PMID 37231359, 2023). "Specific NPY antagonism has not been tried in migraine, but a dual orexin antagonist failed in a clinical trial of migraine, although this was a non-specific drug dosed once at night." (PMID 37569369, 2023). "On the other hand, some investigations did not detect any change in NPY plasma or CSF levels either during or outside of a migraine attack in migraine patients or even reported lower levels of NPY in subjects with migraine than in HC." (PMID 36982428, 2023). "In conclusion, NPY is a good marker of the intracranial sympathetic innervation, but this role in the pathomechanism of migraine pain is still not clear." (PMID 35328439, 2022). "Collectively, we propose that PACAP, NPY, VIP, and nociceptin may play important roles in the pathogenesis of migraine." (PMID 34963819, 2021).
migraine (continued). "To investigate the dynamic changes of the neuropeptides in the rat model of migraine, we measured the mRNA and protein expression of CGRP, PACAP, NPY, VIP, and nociceptin in the TG on the stimulated side and the protein levels of these neuropeptides in the plasma." (PMID 34963819, 2021). "However, the changes in NPY, VIP, and nociception during migraine attacks and their relationship with migraine are still controversial." (PMID 34963819, 2021). "The dynamic changes in neuropeptides after stimulation suggest that CGRP, PACAP, NPY, VIP, and nociceptin may play a role in the pathogenesis of migraine." (PMID 34963819, 2021). "A study in juvenile migraine (both with and without aura) showed significantly lower plasma levels of NPY in the interictal period, with respect to the control group." (PMID 29442286, 2018). "Unfortunately, no clinical trial investigating effectiveness of NPY-related compounds in migraine has been conducted." (PMID 29442286, 2018). "For example, localized release of NPY within hypothalamic nuclei, where we know it is released during feeding and impact migraine symptoms, would not be detected in such assays." (PMID 27023421, 2016). "Whilst no specific NPY agonists have been trialled clinically in migraine, NPY Y1 agonism may hold therapeutic promise as a future target." (PMID 37569369, 2023). "However, other evidence did not observe an NPY immunoreactivity elevation in the suboccipital CSF or plasma during attacks and attack-free periods of patients with migraine without aura." (PMID 35328439, 2022).
myocardial infarction (23 papers, 2017 to 2025). Gross necrosis of the myocardium, as a result of interruption of the blood supply to the area, as in coronary thrombosis. "Lan and colleagues reported NPY deficiency inhibits inflammation in mice with experimental acute kidney injury and acute myocardial infarction by inactivating M1 macrophages." (PMID 38803941, 2024). "Evidence indicates that heightened NPY levels are associated with impaired microvascular function, enhanced myocardial injury, and decreased ejection fraction following myocardial infarction, mediated by the Y1 receptor." (PMID 38803941, 2024). "As a consequence, a therapeutic strategy to prevent NPY‐associated arrhythmias in myocardial infarction and chronic heart failure was suggested (for reviews, see 63, 64)." (PMID 30984535, 2019). "This potential modulator of coronary blood flow has an important role in pathophysiology since higher NPY levels are associated with a higher level of microvascular resistance during myocardial infarction (MI)." (PMID 37029787, 2024). "It has been reported that plasma NPY levels are significantly elevated during myocardial infarction." (PMID 39107876, 2024). "Animal studies indicated that NPY can attenuate cardiac remodeling by inhibiting p38/NF-κB-dependent M1 macrophage activation following acute myocardial infarction in a mouse model." (PMID 38803941, 2024). "The areas with myocardial infarction, myocardial cell apoptosis, and expression and activity of caspase-3 were significantly reduced in NPY-knockout rats, and cardiac systolic function was significantly improved." (PMID 38087221, 2023). "Our recent study also unraveled that NPY acts via Y1R to exert its cardioprotective role in acute myocardial infarction by inhibiting p38/nuclear factor κB (NF-κB)-mediated M1 macrophage activation." (PMID 36632461, 2023). "Further, it has been reported that NPY is involved in the pathogenesis of SC as well as vasospasm and ventricular arrhythmia following myocardial infarction." (PMID 36408384, 2022). "For example, in cases of acute myocardial infarction and congestive heart failure, characterized by high-level sympathetic drive, NPY can be released in addition to NA." (PMID 36408384, 2022). "After myocardial infarction, the sympathetic nervous system is activated with the sympathetic nerve fibers releasing a large amount of NPY, which can aggravate the excessive excitement and uneven distribution of the myocardial sympathetic nerve." (PMID 34471416, 2021). "In summary, we observed action chain of post-myocardial infarction neural remodeling—overactivation of the sympathetic nervous system—large release of neuropeptide Y—promoting cardiomyocyte hypertrophy." (PMID 34471416, 2021). "The results showed that the content of NPY in the tissue and plasma of the marginal area of infarction increased significantly after myocardial infarction." (PMID 34471416, 2021). "NPY demonstrated an important role in stem cell therapy for acute myocardial infarction, by regulating vascular access for progenitor cells, as well as defended the nerves of bone marrow." (PMID 33708805, 2021). "Here, we demonstrated multiplexed detection of two biomarkers of myocardial infarction including cardiac troponin I (cTnI) and neuropeptide Y (NPY) with PRADA with high sensitivity and specificity in patient sera." (PMID 33005736, 2020). "Here, PRADA simultaneously detected two biomarkers of myocardial infarction, cardiac troponin I (cTnI), which is well accepted for cardiac disorders, and neuropeptide Y (NPY), which controls cardiac sympathetic drive." (PMID 33005736, 2020). "In summary, this study presents an innovative biodiagnostic platform, PRADA, demonstrating multiplexed detection of two biomarkers of myocardial infarction, cTnI and NPY, in a simple microfluidic device." (PMID 33005736, 2020). "Animal studies suggest that cardiac NPY is released from sympathetic nerves during experimentally induced myocardial infarction." (PMID 30859228, 2019).
myocardial infarction (continued). "Animal studies suggest that cardiac NPY is released from sympathetic nerves during experimentally induced myocardial infarction although its role in this context is still unclear." (PMID 30283345, 2018). "Neuropeptide‐Y (NPY) is a sympathetic co‐transmitter that is released by sympathetic neurons and circulating venous levels are elevated in a range of cardiac disease, such as myocardial infarction and chronic heart failure." (PMID 38847435, 2025). "Elevated NPY amounts were detected in myocardial infarction cases." (PMID 38803941, 2024). "Neuropeptide Y (NPY) is a cotransmitter that is released alongside norepinephrine from sympathetic nerve terminals, particularly during conditions of sympathetic hyperactivity, such as myocardial infarction." (PMID 35766271, 2022). "We previously found NPY regulated miR-499 in myocardial infarction rat model." (PMID 33390770, 2021). "This suggests that NPY may have an important role in the pathogenesis of post-myocardial infarction arrhythmias in a clinical population, and is an area which warrants further investigation." (PMID 30283345, 2018). "For example, a rat myocardial infarction (MI) model with global NPY knockout exhibited smaller infarct size and lower cardiomyocyte apoptosis compared with WT." (PMID 37460913, 2023). "Thus, given the regulatory effects of NPY on stem cell and the multifaceted beneficial effects on ischemic myocardium, it can be speculated that a combined treatment of stem cells with NPY may be a novel strategy for ischemic heart disease including myocardial infarction." (PMID 29109742, 2017). "As a nonadrenergic and noncholinergic neurotransmitter, NPY can well reflect the activity of sympathetic nerves and the dynamic changes of sympathetic neurotransmitter releasing after myocardial infarction." (PMID 34471416, 2021). "A powerful vasoconstrictor with adverse cardiac inotropic and chronotropic effects, neuropeptide Y (NPY) is a peptide co-localized and co-released with NA from sympathetic nerve terminals, particularly during situations of sympathetic hyperactivity, such as myocardial infarction." (PMID 36012430, 2022).
post-traumatic stress disorder (23 papers, 2014 to 2025). An anxiety disorder precipitated by an experience of intense fear or horror while exposed to a traumatic (especially life-threatening) event. "Endogenous NPY has been suggested as a resilience factor associated with post-traumatic stress disorder (PTSD); however, the underlying mechanisms are still unclear." (PMID 34122036, 2021). "Increased levels of NPY in the amygdala have been linked to coping behavior after repeated exposure to stressors and in an animal model of posttraumatic stress disorder, increased levels of NPY in amygdala and hippocampus have been associated with resilience to traumatic stress." (PMID 24478650, 2014). "NPY is also involved in the development of cardiovascular diseases, anxiety disorders, and posttraumatic stress disorders." (PMID 37836499, 2023). "In agreement with our findings, the ventral hippocampus was involved in the antidepressant effects of NPY in posttraumatic stress disorder." (PMID 36599082, 2023). "At present, several selective NPY receptor agonists and antagonists have been developed and are widely used in research, while nasal delivery of the NPY peptide has been trialed for people with post-traumatic stress disorder." (PMID 34439588, 2021). "For instance, a study in patients suffering from posttraumatic stress disorder demonstrated blunted increases in neuropeptide Y (a stress modulating neuropeptide) in response to a pharmacological stimulant of the stress hormone norepinephrine." (PMID 25396736, 2014). "Clinically, low levels of NPY in plasma and cerebrospinal fluid (CSF) have been suggested as a pathophysiological component of post-traumatic stress disorder (PTSD)." (PMID 40178780, 2025). "In view of the emerging role of NPY in mediating stress resilience and treating post-traumatic stress disorder it appears worth investigating whether pharmacological manipulation of the NPY system has therapeutic effects in animal models of IBD which are sensitive to stress exposure." (PMID 29213271, 2017). "Of interest, single intranasal NPY infusion attenuates development Post-Traumatic Stress Disorder: PTSD-like symptoms to traumatic stress in rat." (PMID 25100947, 2014). "Moreover, a low neuropeptide Y level in CSF correlates with the intrusive memories of trauma, a symptom of post-traumatic stress disorder (PTSD)." (PMID 37375758, 2023). "This is of particular importance as literature has suggested that women may be more vulnerable to stress than men, and a protective role of NPY in stress-related psychiatric disorders, such as post-traumatic stress disorder (PTSD), has been proposed." (PMID 29751614, 2018). "IN NPY has been shown to reach several brain areas, including the hypothalamus, within 30 min in rodents and to suppress behavioral alterations as well as HPA axis activation in a rodent post-traumatic stress disorder (PTSD) protocol." (PMID 31338703, 2019).
type 2 diabetes (22 papers, 2011 to 2025). "Clinically, polymorphisms in NPY have been associated with increased risk of type 2 diabetes and development of diabetic retinopathy." (PMID 34440888, 2021). "To confirm the association of the Leu7Pro polymorphism in NPY with HL activity in a separate group of patients, we assessed the NPY polymorphism in 91 male patients with type 2 diabetes of which HL activity levels were available." (PMID 28638407, 2017). "Consistently, Leu7/Pro polymorphism of NPY gene is associated with increased body mass index, impaired glucose tolerance and type II diabetes, higher serum levels of total and low-density lipoprotein cholesterol, and predicts myocardial infarction and stroke in hypertensive patients." (PMID 34445453, 2021). "Also, IL1B is reported to stimulate the synthesis and release of NPY which also contribute to induction of type-II diabetes in susceptible subjects." (PMID 27749914, 2016). "Autoantibodies to NPY-L (NPY-LA) are present in both individuals with T1D and type 2 diabetes (T2D) but also in healthy siblings to individuals with T1D, thus, suggesting NPY-LA has a genetic component." (PMID 35627254, 2022). "For example when glucocorticoid levels are elevated or during type II diabetes, the pancreatic levels of NPY are reported to increase." (PMID 21559341, 2011). "What is more, acupuncture can effectively reduce plasma neuropeptide Y (NPY), which is one of the main risk factors for the development of type 2 diabetes via constriction of blood vessels and changes in the metabolic environment of the body, especially on lipid metabolism." (PMID 33954169, 2020). "Furthermore, type 2 diabetic Goto-Kakizaki (GK) rats with impaired insulin secretion and action also show hyperphagia and increased expression of NPY in ARC." (PMID 22081645, 2011). "The aim of this study was to test whether the Leu7Pro substitution in NPY is associated with HL activity in subjects with or without type 2 diabetes mellitus." (PMID 28638407, 2017). "This study aimed to investigate the changes of hypothalamic NPY levels and the main hormones that regulate the synthesis and release of hypothalamic NPY, including insulin, leptin, and ghrelin, and may provide additional insights into the study of the pathogenesis of type 2 diabetes." (PMID 27867820, 2016). "Decreased expression of NPY and GAL corresponded with altered feeding behaviors and weight changes in a type 2 diabetes rat model." (PMID 25197671, 2014). "•Increased islet NPY and NPY1R levels are observed in human type 2 diabetes." (PMID 34890851, 2022). "Thus, during the development of the type 2 diabetes, increasing serum concentrations of insulin and leptin, decreasing plasma ghrelin, and declining ghrelin’s stimulation on hypothalamic ARC NPY neurons were observed from the control group to the DIO8W group." (PMID 27867820, 2016).